DMXL1 (Dmx like 1)
Tractability: PROTAC: ubiquitination databases record sites on it; its protein half-life has been measured.
Gene: Protein-coding gene on chromosome 5 (119,037,772 to 119,249,138, forward strand). Ensembl gene ENSG00000172869.
Subcellular location (Human Protein Atlas): Nucleoli; Nucleoli fibrillar center; Cytosol
Gene Ontology:
Biological process: vacuolar acidification
Cellular component: RAVE complex
Genetic constraint (gnomAD): Loss-of-function variants: 73 observed, 247.08 expected, observed/expected ratio (o/e) 0.3, 90% interval 0.24 to 0.36. The upper end of that interval is the gene's LOEUF score, 0.36, which puts it in group 1 of 6, group 1 being the genes least tolerant of losing a copy. Missense variants: 3,269 observed, 3,247.5 expected, observed/expected ratio (o/e) 1.01, 90% interval 0.98 to 1.04. Synonymous variants: 1,211 observed, 1,138.7 expected, observed/expected ratio (o/e) 1.06, 90% interval 1.01 to 1.12.
Homologues: Orthologues: chimpanzee DMXL1 (99% identical), macaque DMXL1 (98% identical), dog DMXL1 (94% identical), pig DMXL1 (93% identical), rat Dmxl1 (90% identical), rabbit DMXL1 (90% identical), mouse Dmxl1 (89% identical), guinea pig DMXL1 (86% identical), tropical clawed frog dmxl1 (73% identical), Drosophila melanogaster Rbcn-3A (40% identical), zebrafish DMXL1 (37% identical), Caenorhabditis elegans rbc-1 (32% identical). Paralogues in human: DMXL2 (56% identical).
Diseases named in the same sentence as DMXL1 in open-access papers:
DMXL1 is named in the same sentence as 9 diseases in open-access papers, as found by Europe PMC text mining. Sharing a sentence is not in itself a finding about the gene and the disease. The quoted sentences say what the papers report.
glaucoma (2 papers, 2010 to 2021). Increased pressure in the eyeball due to obstruction of the outflow of aqueous humor. "Copy number variations in DMXL1 have been associated with glaucoma." (PMID 34249946, 2021). "Whether copy number variations in other genes at the GLC1M locus, such as DMXL1, contribute to glaucoma remain to be investigated." (PMID 21042566, 2010). "DMXL1 is expressed in multiple parts of the eye, and the mechanism of its possible involvement in glaucoma has not been assessed." (PMID 34249946, 2021).
Alzheimer disease (1 paper, 2019). A progressive, neurodegenerative disease characterized by loss of function and death of nerve cells in several areas of the brain leading to loss of cognitive function such as memory and language. "Finally, in the broader context of traits potentially related to cognition, we find an enrichment of HHMCs in genes associated to “Alzheimer’s disease (cognitive decline)” and “Cognitive decline (age-related)”, with seven associated genes (COX7B2, BCAS3, DMXL1, LIPC, PLEKHG1, TTLL2 and VIT)." (PMID 31186485, 2019).
breast carcinoma (1 paper, 2024). "Using machine learning algorithms on multi-omics data from over 6,000 breast cancer patients, we identified six key genes significantly associated with VM and patient risk scores: EP300, PIK3CA, DMXL1, LS, ABL2, and CDK4." (PMID 39165361, 2024).
ear infection (1 paper, 2025). A viral or bacterial infection that affects the external, middle, or inner ear. "Interestingly, an eQTL variant (rs421765) for DTWD2 and DMXL1 has also been associated with severe otitis media (severe ear infection) in Aboriginal Australians." (PMID 40725187, 2025).
cancer (2 papers, 2025). A tumor composed of atypical neoplastic, often pleomorphic cells that invade other tissues. "Intersection analysis of YTHDC2-associated genes with the Catalogue of Cancer Genes (CCG) revealed several cancer-related genes, such as DMXL1, CHD1, and APC, showing strong positive association with YTHDC2 expression." (PMID 41145440, 2025). "Among the other highly DEGs in this cluster, Nup88, Dmxl1 and Igf2bp3 are associated with dysplasia and cancer, including CRC." (PMID 40890536, 2025).
DMXL1 also shares sentences with these, for which no sentence is quoted: cervical cancer (1 paper); Cognitive decline (1); otitis media (1); virus infection (1).